BRCA1 (BRCA1 DNA repair associated)
Diseases named in the same sentence as BRCA1 in open-access papers (continued):
Sharing a sentence is not in itself a finding about the gene and the disease.
breast cancer (continued). "Germline mutations of BRCA1 are known to cause up to 45% of familial breast cancer, while germline aberrations in BRCA1 gene DNA sequences are involved in only 1% of sporadic breast cancer onsets." (PMID 33808555, 2021). "We recommend that a simple test for Polish founder mutations in BRCA1, BRCA2, PALB2 and CHEK2 should be offered to all male breast cancer patients in Poland." (PMID 34461861, 2021). "In the present study, we demonstrated that BRCA1 mutation is associated with GATA3 promoter hypermethylation and reduced GATA3 expression in human breast cancer samples." (PMID 34373738, 2021). "Although BRCA1 and BRCA2 are the most mutated genes, additional genes associated with hereditary breast cancer are emerging." (PMID 34046273, 2021). "In this study, we provide evidence indicating that the spectrum of BRCA1/2 PV found in breast cancer cases from BGP is private compared to that of the rest of Italy." (PMID 33573335, 2021). "The proportion of BRCA1 carriers were approximately twofold higher in Malay breast cancer patients compared to Chinese breast cancer patients." (PMID 34857041, 2021). "For breast cancer screening, 11 genes, including BRCA1 and BRCA2, are recommended for genetic testing in the National Comprehensive Cancer Network guidelines." (PMID 32948841, 2021). "Prompted by the findings derived from mouse models, we then employed human breast cancer samples to determine the correlation of BRCA1 and GATA3." (PMID 34373738, 2021). "Overall, in this study, developed fuzzy logic and neural networks models were found to be successful in predicting correct risk scores for BRCA1 and BRCA2 associated breast cancers, especially classifying VUS variants." (PMID 34828379, 2021). "Of those never having undergone RRBSO, a slightly higher proportion of controls had breast cancer (BRCA1 60.1%, BRCA2 60.4%) and chemotherapy (51.4%/45.4%)." (PMID 33152107, 2021). "In this paper, we aim to study the prevalence and pattern of germline BRCA1 and BRCA2 mutations among a group of young Jordanian patients with breast cancer thought to be at higher risk for such mutations." (PMID 34290354, 2021). "BRCA1 has a large risk-reduction effect on ovarian cancer, whereas BRCA2 has a risk-reduction effect on breast cancer after RRSO." (PMID 32862296, 2021). "Genetic variants in BRCA1 and BRCA2 predispose women to breast and ovarian cancers and are believed to contribute to 5–10% of all breast cancers and 20–40% of familial breast cancers." (PMID 34287743, 2021). "To confirm the role of BRCA1 in controlling Pdgfrβ-Pkcα signaling, we overexpressed WT BRCA1 in two BRCA1-mutant breast cancer cell lines, HCC1937 and SUM149, and a basal-like cell line, MDA-MB231." (PMID 33478572, 2021). "We retrospectively identified at five Italian centers 1019 BRCA1/2 PVs carrier individuals affected with breast cancer and representative of the heterogeneous national population." (PMID 33573335, 2021). "Consistent results were obtained with the breast cancer cell line SUM149PT carrying the BRCA1 2288delT mutation and allelic BRCA1 loss." (PMID 33811064, 2021). "The exome analysis of the BRCA1 and BRCA2 genes in the Amazonian Amerindian populations reported 15 polymorphisms potentially capable of increasing susceptibility to breast cancer." (PMID 33499154, 2021). "We examined frequency and predictors of completion of BRCA1/2 and multigene panel testing and assessed racial/ethnic differences in genetic testing frequency and results among breast cancer patients diagnosed at age ≤ 50 years." (PMID 31802423, 2021).
breast cancer (continued). "For example, germline heterozygous mutations in genes directly implicated in HR—BRCA1, BRCA2, PALB2, RAD51C and RAD51D—increase the risk of ovarian and breast cancer." (PMID 33923105, 2021). "BRCA1-related breast tumours share multiple biological properties with sporadic basal-like breast cancer, therefore we also assessed gene expression variability differences between the basal and non-basal breast tumour subtypes." (PMID 34287743, 2021). "The present study has confirmed some utility for breast cancer gene panels extended beyond BRCA1/2 in women with breast cancer." (PMID 34439310, 2021). "So far, more than 1800 distinct BRCA1 and 2000 BRCA2 mutations have been reported in the Breast Cancer Information Core (BIC) database." (PMID 34490083, 2021). "We describe the first reported case of three concurrent pathogenic germline variants in BRCA1, BRCA2, and CHEK2 associated with inherited breast cancer in an individual." (PMID 33507482, 2021). "In another study, when BRCA1/2 mutant breast cancers were dichotomized by median HRD score, higher HRD scores were also associated with lower immunogenicity." (PMID 34762643, 2021). "Another study using BRCA1 proficient (MCF7) and BRCA1 mutant breast cancer cell lines reported a role for BRCA1 in in vitro breast cancer cell spreading, mobility and wound healing." (PMID 35008272, 2021). "One important reason for different patterns of breast cancer incidence was genes, and it was confirmed that BRCA1/2, HER2, Epidermal Growth Factor Receptor (EGFR), and c-Myc have played key roles in the processes of breast cancer." (PMID 34744569, 2021). "Young breast cancer patients are also more likely to be diagnosed with triple-negative breast cancer (TNBC), which is associated with a higher frequency of BRCA1 mutations." (PMID 31802423, 2021). "Somatic mutations of BRCA1 and BRCA2 in breast cancer are positively correlated with cancer survival." (PMID 34711195, 2021). "Overall 20-year survival in the cohort for all women for breast cancer specific survival was 98.8% (95% CI 98.3–99.1%) and for known BRCA1 carriers (n = 365) = 96.1% (95% CI 90.5–98.4%) and BRCA2 (n = 376) = 91.5% (95% CI 78.6–96.8%)." (PMID 34312777, 2021). "Molecular genetic studies have elucidated breast-cancer susceptibility genes 1 and 2 (BRCA1 and BRCA2) as two major predisposing genes for breast cancer." (PMID 34206661, 2021). "Research has provided evidences that in BRCA1 and BRCA2 mutation carriers peak breast cancer onset is approximately at 30-40 and 40-50 years of age, respectively." (PMID 33773534, 2021). "Pathogenic variants in the breast cancer genes of BRCA1, BRCA2, and PALB2 are common causes of breast cancer in Caribbean women." (PMID 33646313, 2021). "VPA inhibited the protein expression of Rad51 and BRCA1 upon IR treatment in those breast cancer cell lines, which was consistent with the finding in the transformed cells." (PMID 33842359, 2021). "Differences in transcriptome-wide gene expression variability between familial breast cancer groups (BRCA1, BRCA2 and BRCAx) were quantified by comparing tumour-specific measurements of variability (SD, CV and MAD)." (PMID 34287743, 2021).
breast cancer (continued). "The previous study has shown that Wnt3a/GSK3β/Slug/Snail axis controlled EMT programs while coordinately regulating BRCA1 expression in breast cancer." (PMID 33589588, 2021). "In a retrospective study of chemotherapy, naive breast cancer (n = 497) and ovarian cancer (n = 561) patients with known BRCA1/2 status were used to set the cut-off value at ≥42." (PMID 33670893, 2021). "Despite their importance as the major genetic risk factors for breast cancer, pathogenic variants in BRCA1 and BRCA2 account for only ~20% of familial breast cancer risk." (PMID 34439109, 2021). "For example, an investigation of germline variants in 5,391 Slavic patients with breast cancer found 17 breast cancer patients in which two pathogenic variants were detected; 4 (1.4%) of these women were found to be CHEK2 and BRCA1 double heterozygotes." (PMID 33507482, 2021). "The highest detection rate was for grade 3 ER+ HER2− breast cancers with a non BRCA1/2 panel detection rate of 10%." (PMID 34439310, 2021). "The frequency of BRCA1 mutation highly associated with POI, was also investigated in the UK in a study with over two thousand women diagnosed with breast cancer between 1991 and 1996." (PMID 34193292, 2021). "A decrease of BRCA1 expression in response to CCCP treatment was observed in various breast cancer cell lines tested as well as in lung cancer and a neuroblastoma cell line, all of which express wild-type BRCA1." (PMID 33888730, 2021). "In the breast cancer cells, the level of DNp73 induction decreases with BRCA1 depletion after cisplatin treatment." (PMID 34749806, 2021). "We examined EMT markers including Vim, Fn, E-cad, and EMT-TFs and found that all EMT markers positively stained in p18mt;Brca1+/- primary mammary tumors and its related metastasis were also detected in p18mt;Gata3+/-counterparts." (PMID 34373738, 2021). "MiR-146a, miR-146b-5p and miR-182 downregulate BRCA1 protein expression and some reports have shown that different expression of miR-182 in breast cancer cell lines affects their sensitivity to PARPi." (PMID 34552867, 2021). "Brca1 and Mgmt promoter hypermethylation are not limited to breast cancer but are observed in other malignancies such as lung adenocarcinoma." (PMID 34681626, 2021). "A variety of targets, such as estrogen receptor α (ERα), are regulated by BRD7 and BRCA1 coordinately in breast cancer, and BRD7 regulates ERα transcription by recruiting BRCA1 and Oct-1 to the promoter of ESR1 (the gene encoding ERα)." (PMID 34671561, 2021). "We then performed immunostaining for these human breast cancer samples and found that in the ER-positive group, BRCA1-positive tumors whose BRCA1 mRNA levels were equal to or higher than 1.5 expressed moderate to strong GATA3 protein." (PMID 34373738, 2021). "It has been shown that the promoter methylation of MGMT and BRCA-1 were higher in malignant breast tumor (MBT) compared with benign breast tumor (BBT) cases, while the P16 promoter methylation was lower in MBT patients compared with BBT." (PMID 33883026, 2021). "The same differences between BRCA1 and BRCA2 carriers are also apparent regarding the effect of breastfeeding on breast cancer risk." (PMID 34503502, 2021).
breast cancer (continued). "Further, TAMs, which are increased in BRCA1 mutant tumors, are biologically active, inhibiting PARPi activity in BRCA1 mutant breast cancer mouse models." (PMID 34572943, 2021). "BRCA1/BRCA2 mutations account for the majority of hereditary breast cancers, representing about 5–7% of all unselected breast cancers." (PMID 33808562, 2021). "A pathogenic variant in hereditary breast and ovarian cancer (HBOC) predisposing BRCA1 and BRCA2 genes is present in 3–5% of breast cancer cases and 10% of ovarian cancer cases." (PMID 34082720, 2021). "These samples included tumour tissue from 151 BRCA1-associated and 124 BRCA2-associated breast cancer cases." (PMID 34287743, 2021). "BRCA1 and BRCA2 mutations put individuals at higher risk for developing certain malignancies, particularly ovarian and breast cancer." (PMID 34711195, 2021). "For instance, Angelina Jolie’s 2013 disclosure that she had undergone a prophylactic mastectomy resulted in large increases in online breast cancer search queries, followed by a near doubling of demand for BRCA1/2 testing." (PMID 34065061, 2021). "The BRCA1 and BRCA2 genes are mutated in 5–6% of breast cancers and 16% and 6% of ovarian cancers, respectively." (PMID 34316706, 2021). "To further explore the role of PDGFRβ signaling in activating EMT and promoting tumor initiation and progression, we performed a microarray analysis of mammary tumors from p18−/− and p18−/−;Brca1+/− mutant mice." (PMID 33478572, 2021). "We estimated the prevalence of 20 alleles in six genes (BRCA1, BRCA2, CHEK2, PALB2, NBN, RECQL) in 165 Polish male breast cancer patients." (PMID 34461861, 2021). "Since the mid-1990, extensive efforts have been dedicated to the analysis of BRCA1 and BRCA2, the two most commonly mutated breast cancer genes." (PMID 34456966, 2021). "Five CpG sites were investigated to confirm the enrichment of methylated DNA sites, which previously have been documented to be strongly correlated with very low BRCA1 expression in breast cancer cell lines." (PMID 34601813, 2021). "Both contralateral breast cancer and ovarian cancer occurrence were more frequent in BRCA1 than BRCA2 carriers." (PMID 34490083, 2021). "Finally, most guidelines relating to carriers of pathogenic BRCA1/2 variants recommend annual magnetic resonance imaging (MRI) in combination with mammography and/or ultrasound as a screening tool to maximise the sensitivity of breast cancer screening in this group." (PMID 33836815, 2021). "Nonetheless, similar data have been found in a phase II trial that evaluated talazoparib in patients with advanced HER2-negative breast cancer or other solid tumors with a germline or somatic alteration in HRR-related genes other than BRCA1/2." (PMID 33800556, 2021). "Here, we applied dropseq to analyze pair-matched mammary gland cells and mammary tumor cells from two Brca1 mutant mice (termed as MT1 and MT2 hereafter)." (PMID 34815798, 2021).
breast cancer (continued). "Although the genomics features of mouse Brca1 mammary tumors have recently been analyzed by WES30,43, such analyses have not been reported for mouse Brca2 and Palb2 tumors." (PMID 33893322, 2021). "Carriers of pathogenic variants of BRCA1 and BRCA2 are referred to an intensified surveillance, including clinical examination, ultrasound, mammography and MRI scan in order to detect breast cancer at an early stage." (PMID 33921890, 2021). "To further investigate this possibility in cells with a naturally-occurring pathogenic BRCA1 mutation, we generated two independent SHLD2 knockout clones (G1 and D1) from BRCA1 mutant MDA-MB-436 breast cancer cells." (PMID 34140467, 2021). "Breast cancer genes BRCA1 and BRCA2 play a role in DNA repair and co-localise in the nuclear foci with RAD51, a protein required for homologous recombination within a, probably common, DNA repair pathway." (PMID 34577828, 2021). "We discovered that GATA3 functions downstream of BRCA1 to suppress EMT in controlling mammary tumor initiation and metastasis." (PMID 34373738, 2021). "Previous studies reporting large gene panels in breast cancer have mainly reported on the contribution of additional genes compared to BRCA1/2." (PMID 34439310, 2021). "For several decades, physicians have modeled genetic susceptibility to breast cancer with BRCA1 and BRCA2 variants to characterize women’s predisposition to breast cancer incidence and recurrence." (PMID 34038146, 2021). "Further studies showed that males who harbored a germline BRCA1 and BRCA2 mutation, identified via a family history of breast cancer, were reported to have an increased the risk of PCa by three-fold and seven-fold, respectively." (PMID 34830851, 2021). "The prevalence of germline BRCA1 and BRCA2 mutations is 5–15% in breast cancer (BC) and 10–25% of ovarian cancer (OV) patients." (PMID 33525353, 2021). "An important correlation also exists between germ-line mutations in breast cancer susceptibility genes 1 and 2 (BRCA1 and BRCA2), which are associated with a 40–85% lifetime breast cancer risk, and AR structure and transcriptional activity." (PMID 35008851, 2021). "After a genetic assessment, 69% (30/43) met criteria for genetic testing, which comprised of 56.6% (17/30) breast cancer panel tests, 36.6% (11/30) BRCA1/2 only tests and 6.6% (2/30) predictive tests." (PMID 33637119, 2021). "One also sees that somatic mutations of BRCA1 or BRCA2 associate with additional up-regulated spots compared to their germline counterparts (for example compare gBRCA1 and sBRCA1 portraits for breast cancer, or gBRCA2 vs. sBRCA2 portraits for ovarian cancer)." (PMID 33525353, 2021). "Among the identified mutations c.211dupA, c.5266dupC in BRCA1 and c.1310_1313delAAGA in BRCA2 were the most recurrent mutations encountered among the hereditary breast cancer cases." (PMID 34490083, 2021). "BRCA1 was also described to reduce breast cancer cell migration through ubiquitination of ezrin–radixin–moexin protein complex that is important in regulation of cellular motility and spreading." (PMID 33540843, 2021). "The top three phenotypes for the BRCA1 gene were ovarian cancer, breast cancer and cancer, and the top three phenotypes for the STAT3 were prostate cancer, retinoblastoma, and Buckley syndrome." (PMID 34315992, 2021).